ENSG00000268870 (novel zinc finger protein)
Gene: Protein-coding gene on chromosome 19 (12,391,949 to 12,441,082, reverse strand). Ensembl gene ENSG00000268870.
Genetic constraint (gnomAD): Loss-of-function variants: 2 observed, 5.35 expected, observed/expected ratio (o/e) 0.37, 90% interval 0.15 to 1.17. That is too few expected variants to judge how well the gene tolerates losing a copy. Missense variants: 112 observed, 129.32 expected, observed/expected ratio (o/e) 0.87, 90% interval 0.74 to 1.01. Synonymous variants: 26 observed, 38.89 expected, observed/expected ratio (o/e) 0.67, 90% interval 0.49 to 0.93.